FOSL2 (FOS like 2, AP-1 transcription factor subunit)
Diseases named in the same sentence as FOSL2 in open-access papers (continued):
Sharing a sentence is not in itself a finding about the gene and the disease.
tumor (82 papers, 2005 to 2026). "The transcription factor FOSL2 is associated with the hypoxic status of the tumour and has been related to the extent of necrosis in GBM samples and as governing a MS transcriptional signature in GBM." (PMID 37357610, 2023). "FOSL2 deficiency has been mostly correlated with tumor suppression, validating its potential as a possible therapeutic target." (PMID 35805190, 2022). "Similarly, loss of Wnt5a, the direct target of FOSL2, in CAFs significantly decreased tumor blood vessel formation and tumor growth." (PMID 33754039, 2021). "However, additional studies are needed to confirm the findings and determine whether such up-regulation is caused by FOSL2 overexpression in HCC tumor tissues." (PMID 26487969, 2015). "The levels of genes associated with tumor metastasis, including MAPK1, MAPK14, COL5A1, FN1, EP300, and FOSL2, were significantly downregulated after SH intervention." (PMID 41444284, 2025). "The results demonstrated a significant inhibition of FOSL2 expression in tumor cells upon addition of a neutralizing antibody against TGFβ." (PMID 39899538, 2025). "The AP-1 complex consists of Jun family members (JUNB, c-JUN, JUND and v-JUN) and Fos family members (FOS, FOSB, FOSL1 and FOSL2), which directly promotes PD-L1 expression in tumor cells." (PMID 40599804, 2025). "To elucidate the mechanism by which M2‐like macrophages promote elevated expression of FOSL2 in tumor cells, we employed neutralizing antibodies against various M2‐like macrophage‐associated cytokines and growth factors in our co‐culture system." (PMID 39899538, 2025). "Co‐immunoprecipitation (co‐IP) experiments demonstrated physical bonding between MYC and FOSL2 in M‐M2 tumor cells." (PMID 39899538, 2025). "Our data support that in MP‐subtype LUAD, recruited M2‐like macrophages stimulate tumor cell FOSL2 expression through secreting TGFβ, thereby increasing accessibility to novel MYC chromatin binding sites." (PMID 39899538, 2025). "The exogenous addition of recombinant human TGFβ effectively promoted the expression of FOSL2 in tumor cells." (PMID 39899538, 2025). "The peri-necrotic zone and pseudo-palisading cells around necrosis showed significantly higher mRNA levels of JUN, JUNB, FOS, and FOSL2 compared to other regions of the tumor, such as the leading-edge, infiltrating tumor, and cellular tumor." (PMID 39257581, 2024). "A comparison of EGR1, FOS, IER2, JUN, KLF6, MYC, and FOSL2 gene expression in 481 tumor samples revealed that individual tumors vary substantially in the expression of all analyzed genes." (PMID 39436655, 2024). "FOSL2 is known as a member of the activator protein-1 (AP-1) family, which plays important roles in multiple aspects of tumor development." (PMID 38286983, 2024). "More importantly, cluster 2 exhibits a strong positive correlation with transcription factors WNT5A, WNT10A, GATA2, and FOSL2, all recognized for their involvement in tumor stemness." (PMID 38339238, 2024). "We observed that the expression of MUC5AC was absent in ductal cells from normal samples but enriched in part ductal cells from tumour samples, while FOSL2 was up-regulated in ductal cells from tumour samples compared to ductal cells from normal samples." (PMID 37380804, 2023). "TCGA bulk RNA-seq also showed higher CCL28 expression in PDAC tumour tissues than in normal tissues and was positively correlated with FOSL2." (PMID 37380804, 2023). "Immune cell composition analysis revealed a notable reduction in CD8+ T cell infiltration in oe-FOSL2 tumours." (PMID 37380804, 2023). "In conclusion, these results suggested that CCL28 mediated FOSL2-driven tumour growth and Treg cell infiltration." (PMID 37380804, 2023). "In the immune pathway, we found that FOSL2 promoted tumour growth, decreased CD8+ T cell infiltration, and increased Treg cell recruitment in immunocompetent C57BL/6 mice." (PMID 37380804, 2023).
tumor (continued). "The same variant has been reported in two types of carcinomas in cBioPortal, and several studies point towards an oncogenic potential of FOSL2 in tumor cell growth and metastasis." (PMID 37046633, 2023). "Immunofluorescence staining for CD31 indicated increased angiogenesis in oe-FOSL2 tumour but was reversed with anti-CCL28-treated tumours." (PMID 37380804, 2023). "To this end, we stained for FOSL2 protein expression in tumor sections from GBM, PAAD, merkel cell carcinoma (MCC) and PRAD." (PMID 36932385, 2023). "The results showed that the expression of FOSL2 was significantly up-regulated in PDAC tissues compared to non-tumour tissues." (PMID 37380804, 2023). "Upon the observation of high FOSL2 gene expression in aggressive tumors, we investigated this association in patient specimens and PAAD tumor models." (PMID 36932385, 2023). "Fosl2 is differentially expressed in many tumors and is essential to cell cycle regulation and tumor proliferation." (PMID 36062065, 2022). "Copy number gains of CEP63 (p<0.01) and FOSL2 (p=0.046) were found to be correlated with advanced tumor stage." (PMID 34041036, 2021). "Previous tumor bulk analysis identified a related AP-1 family member FOSL2, together with CEBPB, STAT3, and TAZ, as important regulators of the MES GBM subtype." (PMID 34399888, 2021). "Copy number gains of CEP63 and FOSL2 were correlated with advanced tumor stage and high tumor grade (p<0.01 and p=0.047, respectively)." (PMID 34041036, 2021). "Real-time PCR results showed that compared with the 49 healthy control urine sediment samples, copy numbers of CEP63 (p=0.036) and FOSL2 (p<0.01) were significantly gained in BC urine sediment samples, which was consistent with the results in tumor samples." (PMID 34041036, 2021). "Taken together, these findings demonstrate that EphA2-SE plays an oncogenic role and promotes tumor progression in various tumors by recruiting FOSL2 and TCF7L2 to drive the expression of oncogene EphA2." (PMID 33712565, 2021). "Several studies have reported that the phosphorylation and upregulation of FOSL2 enhance tumor growth and invasion in A549 cells through miR-638." (PMID 34938346, 2021). "The FOSL2 protein levels in tumor tissues were closely related to the Wnt5a concentration in tumor extracts." (PMID 33754039, 2021). "Results suggested that EphA2-SE recruits TCF7L2 and FOSL2 through the core component E1 to directly target EphA2 and promote tumor progression in cancer cells." (PMID 33712565, 2021). "Meanwhile, the denser microvessel density (MVD), which was evaluated by CD31 staining, was greater in stromal FOSL2 highly expressed tumor tissues than in stromal FOSL2 low expressed tissues (p<0.001)." (PMID 33754039, 2021). "In vivo studies confirmed that overexpression of FOSL2 or silencing of miR-638 led to the recovery of tumor growth ability regarding A549 cells after hsa_circ_0001869 knockdown." (PMID 33221767, 2020). "hsa_circ_0001869 downregulation decreased tumor proliferation, invasion and migration by promoting miR-638 expression and decreasing FOSL2 expression." (PMID 33221767, 2020). "In vivo xenograft mouse models developed through A549 cells illustrated that miR-638 downregulation or FOSL2 upregulation resulted in tumor growth ability recovery regarding A549 cells after hsa_circ_0001869 knockdown." (PMID 33221767, 2020). "Additionally, elevated FOSL2 expression in the subcutaneous tumor samples was consistently accompanied by increased TGFβR1 expression." (PMID 39899538, 2025). "Notably, JUND and FOSL2 were consistently found to be significant players in all types of tumor-specific domains." (PMID 41323280, 2025). "This specificity may be attributed to the selective recruitment of key TFs, such as FOSL2, to the SE regions in these tumor types, highlighting a potential mechanism for EFNA1-SE–driven oncogenesis in CC and beyond." (PMID 39964764, 2025).
tumor (continued). "We then observed that the decrease in 5-FU resistance induced by FOSL2 knockdown in the nude mouse subcutaneous tumor model could be rescued by SEMA3C overexpression." (PMID 40082673, 2025). "Spatially, we observed co‐localization of MYC and FOSL2 in the nucleus of M‐M2 tumor cells." (PMID 39899538, 2025). "Additionally, FOSL2 downregulation remarkably decreased tumor volume in the 4T1 animal model and cell growth and metastasis in 4T1 and MDA-MB231 cells." (PMID 39010083, 2024). "A recent study reported that the FOSL2 transcription factor could drive the expression of oncogene EphA2 to induce cell proliferation, metastasis, and tumor progression in various tumors." (PMID 39010083, 2024). "In addition, we discovered that cluster 2 is highly associated with some tumor stemness-related transcription factors: WNT5A, WNT10A, GATA2, and FOSL2." (PMID 38339238, 2024). "Moreover, ZN444B treatment induces P21 expression and decreases vimentin expression, implying that FOSL2 is involved in tumor progression and metastasis." (PMID 39010083, 2024). "Additionally, EdU staining once again confirmed the decreased proliferative capacity of tumor cells after FOSL2 knockdown." (PMID 39403379, 2024). "Previous studies have demonstrated that FOSL2 is essential for tumor growth and metastasis." (PMID 39010083, 2024). "Integrating scRNA-seq of multifocal GBMs identified FOSL2 as one of the hallmarks of higher expression in older lesions that may be involved in tumor evolution." (PMID 37705736, 2023). "Our results also showed that FOSL2 depletion markedly reduced tumour cell proliferation." (PMID 37380804, 2023). "Functionally, we observed that FOSL2 overexpression increased tumour growth and Treg cell infiltration, which could be reversed by blockade of CCL28 activity in vivo, indicating its potential as a therapeutic target." (PMID 37380804, 2023). "Strikingly, FOSL2 overexpression significantly accelerated tumour growth." (PMID 37380804, 2023). "Interestingly, the same top-ranked motifs were bound by key TFs essential for tumor metastasis and invasion, including Fosl2 and JUN." (PMID 37479693, 2023). "We found that immune signalling was suppressed in the high FOSL2 group, implying that FOSL2 might promote PDAC progression by inhibiting the tumour immune microenvironment." (PMID 37380804, 2023). "CNVs of CEP63 and FOSL2 were correlated with advanced tumor stage and high grade." (PMID 34041036, 2021). "CNVs of CEP63 and FOSL2 were correlated with tumor stage and histologic grade." (PMID 34041036, 2021). "As expected, FOSL2 is expressed in tumor and met at both the RNA and protein levels." (PMID 34593797, 2021). "Collectively, the current study suggests that targeting FOSL2 in stromal CAFs may be an effective alternative to overcome tumor refractoriness to anti-VEGF signaling treatment." (PMID 33754039, 2021). "The high level of stromal FOSL2 was significantly related to tumor stage." (PMID 33754039, 2021). "However, the protein level of FOSL2 is significantly higher in tumor and met compared to normal (FDR < 0.1)." (PMID 34593797, 2021). "In this study, we identified that the transcriptional factor FOSL2 may act as a novel tumor angiogenesis target in breast CAFs." (PMID 33754039, 2021). "However, treatment of tumor burden mice injected with FOSL2-overexpressing NFs using BOX5 (Wnt5a antagonist) mitigated FOSL2-stimulated blood vessels and tumor growth." (PMID 33754039, 2021). "The tumor burden mice injected with NFs had fewer blood vessels and small tumors, and ectopic FOSL2 in NFs could significantly promote blood vessels and tumor growth." (PMID 33754039, 2021). "In addition to MYC, many tumor-associated genes such as RUNX1, FOSL2, BCL3 and ID2 are driven by SEs in diverse tumor types." (PMID 33628735, 2020). "Notably, miR-143 is a tumor suppressor that negatively correlates with cisplatin resistance and is believed to exert its action, at least in part, through silencing FOSL2 gene expression." (PMID 32854207, 2020).
tumor (continued). "FOSL2 is a member of the Fos family of transcription factors that heterodimerize with the Jun family members to form the AP-1 complex, which is able to activate or suppress the expression of many genes involved in tumor growth and progression." (PMID 30326930, 2018). "In contrast to blockage of VEGF signaling alone by anti-VEGF antibody, FOSL2 knockdown in CAFs combined with VEGF signaling inhibitors could augment the suppressive efficiencies to tumor angiogenesis, indicating that FOSL2 acted as an obviously proangiogenic effector in the VEGF-independent pathway." (PMID 33754039, 2021). "Although the ranking order may vary, the majority of the top-ranked TEff/EM regulons such as Rora, Fosl2, Creb3, Maf, Prdm1, Nfil3, and Nfkb1 were also identified as top-ranked regulons for active TRMs in the tumor and distant mammary mucosa." (PMID 33979626, 2021). "In addition, we found that knockdown of FOSL2 in CAFs could increase the sensitivity of tumor cells to VEGF inhibitors in vivo." (PMID 33754039, 2021). "Results showed that copy numbers of CEP63 (p<0.01) and FOSL2 (p<0.01) were significantly gained in 40 BC urine sediment samples compared with 42 control urine sediment samples, which was consistent with the real-time PCR results of tumor samples and 123 urine sediment samples." (PMID 34041036, 2021). "Consistently, treating mice with Wnt5a, the critical pro-angiogenic factor regulated by FOSL2, could partly rescue blood vessels and tumor growth of tumor burden mice injected with FOSL2-silenced CAFs (labeled CAF/shFOSL2 + rWnt5a) in comparison to their control tumors (labeled CAF/shFOSL2)." (PMID 33754039, 2021). "Given that TGF-β1 can utilise various programmes to promote cancer metastasis through its effects on the tumour microenvironment, enhanced invasive properties, and inhibition of immune cell function, our findings also reveal that FOSL2 may increase invasive potential through the TGF-β pathway." (PMID 25375657, 2014). "In accordance with these findings, individual and combined knockdown of FOSL2 and KLF6 compromised the 5-FU resistance of HCT15-FR cells in a nude mouse subcutaneous tumor model." (PMID 40082673, 2025). "The transcriptional programs regulated by TBX21, ZNF595, FOSL2, ZNF83, ZNF484, IKZF2, and ELK3 were found to be significantly activated in tumor-reactive T cells." (PMID 39243082, 2024). "The enrichment of FOSL2 protein in the peri-necrotic zone and pseudopalisading cells area was further confirmed by in situ hybridization (ISH) and H&E staining with tumor feature annotations." (PMID 39257581, 2024). "Our data demonstrate the implication of SOX2 in promoting DNA damage and genome instability by sustaining inflammation via FOSL2/IL6, resulting in tumor aggressiveness." (PMID 36932385, 2023). "Although the percentages of CD4+ cells were similar in oe-FOSL2 and vector tumour samples, the number of CD4+CD25+ Foxp3+ Tregs was increased in oe-FOSL2 tumours." (PMID 37380804, 2023). "To explore the specific cell type of FOSL2 expression, we reanalysed public scRNA-seq data consisting of 24 PDAC tumour tissues and 11 control pancreas tissues." (PMID 37380804, 2023). "Dimers of FOS (c‐FOS, FOS‐B, FRA‐1/FOSL1 and FRA‐2/FOSL2) and JUN (c‐JUN, JUN‐B, and JUN‐D) build the AP1 complex, which can drive tumor progression and treatment resistance." (PMID 35604882, 2022). "In several tumor tissue studies, miR-143-3p was significantly downregulated and acted as a tumor suppressor by silencing genes which promoted cell proliferation and invasion, i.e., COX-2 in gastric cancer, FOSL2 in osteosarcoma, and KRAS in PitNET." (PMID 33808624, 2021). "Results showed that compared with the control group, copy numbers of 3 genes, CEP63 (p<0.01), FOSL2 (p<0.01) and PAQR6 (p<0.01) were significantly gained in tumor tissues." (PMID 34041036, 2021).
tumor (continued). "It is known from other cancers, that FOSL2 is activated by the ERK1/2 kinase leading to the transcription of SNAI2, which plays an important role in tumor metastasis via activation of epithelial-to-mesenchymal transition (EMT)." (PMID 34073664, 2021). "According to our study, FOSL2 CNVs were independent prognostic factors for both NMIBC and MIBC, indicating their important role in tumor progression." (PMID 34041036, 2021). "The results indicated that tumor tissues showed increased PES1 and FOSL2 expression compared with NCTs." (PMID 34782005, 2021). "FOS-related antigen 2 (FOSL2) belongs to the AP-1 family of transcription factors and plays an important role in tumor proliferation and cell cycle regulation." (PMID 35003395, 2021). "Fos-related antigen 2 (FRA-2/FOSL2) belongs to the AP-1 transcription factor family and plays a critical role in tumor growth and metastasis." (PMID 32854207, 2020). "Results confirmed that BLCAP, EML1, FOSL2, ADNP and FRMD3 were deregulated in the same way among the xenografts, FFPE and OCT tumour samples." (PMID 30592148, 2019). "We also demonstrated the co-operative function of RUNX1 and FOSL2 in maintaining the expression of SNAI2, a key mediator of epithelial–mesenchymal transition and tumor dissemination." (PMID 30903020, 2019). "In an in vivo model, knockdown of FOSL2 in MYC‐overexpressing mouse LLC cells prior to establishing the C57BL/6J xenograft model did not alter subcutaneous tumor growth rate but greatly reduced CTC numbers and dissemination index." (PMID 39899538, 2025). "For PD, we identified 115 TFs, TFBSs for three of which were significantly enriched in tumor-specific PDs: FOSL2, JUND, and TFAP2A, whereas no significant enrichment was found in normal-specific PDs." (PMID 41323280, 2025). "Through a comprehensive workflow combining H3K27ac-ChIP-seq and RNA-seq analyses, we identified critical TFs and tumor-specific super-enhancer domains (T-SEDs) that regulate gene expression in HPV+ HNSCC, such as TP63, SMAD3, FOSL2, JUND, JUNB, KLF5, and TFAP2A." (PMID 41323280, 2025). "We observed that tumor growth rate was not attenuated by FOSL2 absence, while the quantity of CTCs and the dissemination index in peripheral blood were significantly decreased." (PMID 39899538, 2025). "The KLF6, MYC, and FOSL2 genes did not seem to follow the EGR1/FOS expression pattern in the analyzed tumor samples." (PMID 39436655, 2024). "CAFs with high expression of FOS-like antigen 2 (FOSL2) can promote angiogenesis and tumor growth." (PMID 37666813, 2023). "Studies have reported that FOSL2 can interact with Smad3, Wnt5a, or SNAI2 to promote tumour growth." (PMID 37380804, 2023). "Mutations of the remaining two FOS genes, FOS Like 1 (FOSL1) and FOS Like 2 (FOSL2), have not been demonstrated in human tumours to date." (PMID 36426824, 2023). "Collectively, we found that SNHG17 exerts tumor-promoting functions through PES1 and FOSL2." (PMID 34782005, 2021). "The increased FOSL2 in CAFs plays a pivotal role in promoting angiogenesis by regulating Wnt5a, thus stimulating activation of the downstream FZD5/NF-κB/ERK signaling axis in vascular endothelial cells to fuel tumor angiogenesis VEGF-independent patterns." (PMID 33754039, 2021). "The supernatant from CAFs highly expressing FOSL2 strongly promoted tube formation and sprouting of human umbilical vein endothelial cells (HUVECs) in a VEGF-independent manner and angiogenesis as well as tumor growth in vivo." (PMID 33754039, 2021). "Copy numbers of CEP63, FOSL2 and PAQR6 were gained in 219 tumor samples." (PMID 34041036, 2021). "In addition, we examined protein levels of several LPS141 tumor-promoting genes (i.e., RUNX1, c-MYC, FOSL2, RUNX2, and SNAI2) after ETC-168 treatment." (PMID 33564073, 2021). "Moreover, our clinical results of a correlation between FOSL2 and activated Smad3 expression in NSCLC tumours further confirm this conclusion." (PMID 25375657, 2014).